LCNL1 (lipocalin like 1)
Synonyms: FLJ45224
Tractability: No criterion of Open Targets' tractability assessment is met for any kind of drug.
Gene: Protein-coding gene on chromosome 9 (136,981,904 to 136,986,410, forward strand). Ensembl gene ENSG00000214402.
Gene Ontology:
Molecular function: small molecule binding
Genetic constraint (gnomAD): Loss-of-function variants: 11 observed, 6.56 expected, observed/expected ratio (o/e) 1.68, 90% interval 0.99 to 1.95. That is too few expected variants to judge how well the gene tolerates losing a copy. Missense variants: 218 observed, 189.19 expected, observed/expected ratio (o/e) 1.15, 90% interval 1.03 to 1.29. Synonymous variants: 90 observed, 77.86 expected, observed/expected ratio (o/e) 1.16, 90% interval 0.97 to 1.38.
Homologues: Orthologues: dog LCNL1 (45% identical). Paralogues in human: LCN15 (23% identical), LCN8 (18% identical), OBP2A (16% identical), PTGDS (16% identical), LCN10 (15% identical), OBP2B (15% identical), LCN12 (14% identical), LCN2 (13% identical), LCN6 (13% identical), LCN9 (13% identical), LCN1 (12% identical), PAEP (9% identical).